BECN1 (beclin 1)
Diseases named in the same sentence as BECN1 in open-access papers (continued):
Sharing a sentence is not in itself a finding about the gene and the disease.
rhabdomyosarcoma (2 papers, 2014 to 2020). A rare aggressive malignant mesenchymal neoplasm arising from skeletal muscle. "Blocking of autophagy also attenuates cell death caused by the avian influenza A H5N1 virus both in vitro and in vivo, and it is known that knockdown of beclin-1 or Atg5 protects human rhabdomyosarcoma cells from enterovirus 71-induced apoptotic death." (PMID 24490870, 2014).
Salmonella Infections (2 papers, 2018 to 2023). Infections with bacteria of the genus SALMONELLA. "Salmonella infection down-regulated the expression of the following protein biomarkers of autophagy (a catabolic process for stress adaptation of cellular components): Beclin-1, Atg5, Atg12, Atg16, LC3-I and LC3-II." (PMID 30518352, 2018). "The results show that Salmonella infection down-regulated expression of the autophagy-related proteins including Beclin-1 compared with the uninfected controls." (PMID 30518352, 2018). "Although p38MAPK/MK2/MK3 regulated autophagy by phosphorylation of Beclin-1 at Serine 90 upon starvation in HeLa cells has been described, it still remains open whether the regulation of autophagy by p38MAPK/MK2 upon Salmonella infection in MEFs follows the same mechanism." (PMID 37771590, 2023).
serous ovarian cancer (2 papers, 2015 to 2020). "Furthermore, BECN1 localizes to the long arm of chromosome 17, a region that sees a high frequency of monoallelic loss in high-grade serous ovarian cancer (HGSC)." (PMID 26239434, 2015).
serous ovarian tumors (2 papers, 2015 to 2019). "Here we demonstrate that even with prevalent BECN1 single-copy loss, Beclin-1 protein expression remains similar across 398 high-grade serous ovarian tumors." (PMID 26239434, 2015). "However, there was a study demonstrated that the expression of BECN1 was retained in high-grade serous ovarian tumors although a prevalent monoallelic deletion of BECN1 gene was observed in TCGA database." (PMID 31272261, 2019). "In order to assess the relationship between BECN1 copy-number and expression, we interrogated level 3 array comparative genomic hybridization (aCGH) and RPPA data generated by TCGA from a large number of high-grade serous ovarian tumors (91 % of which are from metastatic, stage III-IV disease)." (PMID 26239434, 2015).
subarachnoid hemorrhage (2 papers, 2023). A serious neurological disorder characterized by intracranial hemorrhage into the subarachnoid space. "In addition, knockdown of BECN1 was found to improve early brain injury (EBI) after subarachnoid hemorrhage (SAH) by increasing xCT activity and inhibiting lipid peroxidation." (PMID 37745084, 2023). "Finally, enhancing autophagy by increasing beclin-1 inhibited the apoptotic process, where it was previously documented that enhancing autophagy in the early stages of brain injury after a subarachnoid hemorrhage protected neurons against neural apoptosis through a mitochondrial pathway." (PMID 36976198, 2023).
tauopathy (2 papers, 2015 to 2023). Neurodegenerative disorders involving deposition of abnormal tau protein isoforms (tau proteins) in neurons and glial cells in the brain. "This hypothesis is consistent with our observations of reduced levels of Vps34 total protein that were strongly associated with Beclin-1 at 30 days post-ischemia, which coincided with the decline of tauopathy levels in this time point." (PMID 26042033, 2015).
Thrombocytopenia (2 papers, 2023). A reduction in the number of circulating thrombocytes. "Patients with severe thrombocytopenia displayed significantly higher expression levels of MLKL and Beclin-1 than those who had moderate thrombocytopenia (4.03 ± 0.63 and 4.73 ± 0.56 vs 1.54 ± 0.22 and 1.99 ± 0.33, respectively)." (PMID 35699825, 2023). "Furthermore, the degree of thrombocytopenia was positively correlated with both MLKL and Beclin-1 expression levels." (PMID 35699825, 2023).
tuberculosis (2 papers, 2012 to 2016). A chronic, recurrent infection caused by the bacterium Mycobacterium tuberculosis. "A third miRNA implicated in the inhibition of autophagy by M. tuberculosis is miR-30a and this was predicted to act upon beclin-1 since monocytes isolated from tuberculosis patients exhibited a negative correlation between the concentrations of miR-30a and beclin-1." (PMID 27536558, 2016). "tuberculosis treated Beclin-1 RNAi transduced cells was not significant (P = 0.36)." (PMID 22589721, 2012).
ulcerative colitis (2 papers, 2021 to 2022). An inflammatory bowel disease involving the mucosal surface of the large intestine and rectum. "Therefore, the reduced beclin-1 expression in the current model of ulcerative colitis could be due to the diminished AMPK activity." (PMID 34489707, 2021).
uremia (2 papers, 2021 to 2022). A clinical syndrome associated with the retention of renal waste products or uremic toxins in the blood. "Furthermore, we found, by examining autophagy marker proteins (Beclin-1, LC3-II, and beclin-1) in the hearts of mice that underwent 5/6 nephrectomy and serum uremia-treated H9C2 cardiomyocytes, that supplementation with NaHS or L-Cys could decrease excessive autophagy activity." (PMID 36588697, 2022).
ZIKV infection (2 papers, 2020 to 2023). "Specifically, we showed that a reduced expression of Beclin1 aggravated the consequences of ZIKV infection on brain development and qualifies Becn1 as a susceptibility gene of ZIKV congenital syndrome." (PMID 32498399, 2020). "The reduced expression of Beclin1 aggravated the consequences of ZIKV infection on brain development and qualifies Becn1 as a susceptibility gene of ZIKV congenital syndrome." (PMID 32498399, 2020). "We explored the role of Beclin1 in ZIKV infection and disease using timed pregnancy in reduced Beclin1-expressing (Becn1+/−) and wild-type (Becn1+/+) mice models." (PMID 32498399, 2020). "ZIKV infection of human umbilical vein endothelial cells can modulate the AKT/mTOR and BECN1 signalling pathways to induce autophagy and enhance viral replication." (PMID 37936178, 2023).
acute lung injury (1 paper, 2022). A condition of lung damage that is characterized by bilateral pulmonary infiltrates (pulmonary edema) rich in neutrophils, and in the absence of clinical heart failure. "Our study aimed to investigate the effect of electroacupuncture pretreatment on the inflammatory response and expression levels of LC3-II/I and Beclin 1 using a model of lipopolysaccharide (LPS)-induced acute lung injury (ALI)." (PMID 36310624, 2022).
adenovirus infection (1 paper, 2024). "Additionally, the mcherry-EGFP-LC3 adenovirus infection and Western blotting results showed that the number of autophagosomes, Beclin 1 protein abundance, and LC3-II/LC3-I ratio decreased after HMGB1 knockdown." (PMID 38468340, 2024).
adrenal cortical tumor (1 paper, 2021). "LC3A, LC3B, beclin-1, and LC3B isolated single positive cells (ISPC) positivity rates were higher in PCC than in adrenal cortical tumor (ACT), whereas p62 positivity was lower in PCC than in ACT." (PMID 34638836, 2021).
adrenal gland tumors (1 paper, 2021). "The aim of this research was to evaluate the expression and concomitant implications of LC3A, LC3B, beclin-1, and p62, which are key components of autophagy in human adrenal gland tumors." (PMID 34638836, 2021). "The aim of this study was to investigate the expression and implication of key autophagy components, LC3A, LC3B, beclin-1, and p62, in human adrenal gland tumors." (PMID 34638836, 2021).
anaplastic thyroid carcinoma (1 paper, 2015). "Inhibition of beclin 1-mediated autophagy by miR-30d mimic sensitized anaplastic thyroid carcinoma cells to cisplatin." (PMID 26666173, 2015).
Anxiety (1 paper, 2025). Intense feelings of nervousness, tension, or panic often arise in response to interpersonal stresses. "In this study, we investigated whether the transgenic disruption of stimulus-induced autophagy, by targeting the BECLIN-1 protein, would affect the development of chronic neuropathic pain and associated anxiety-like behavior in female and male mice." (PMID 39809538, 2025). "This suggests that one possible mechanism through which BECLIN-1 disruption alters nociceptive hypersensitivity and anxiety-like behaviors in male mice is through altering injury-related immune responses, including the release of IL-1β." (PMID 39809538, 2025). "We also found that disruptions of BECLIN-1 prevented SNI-induced increases in anxiety-like behaviors in male mice." (PMID 39809538, 2025). "Using the spared nerve injury (SNI) model of neuropathic pain, we found contrasting roles for BECLIN-1 in the development of pain hypersensitivity and anxiety-like behaviors in a sex-dependent manner." (PMID 39809538, 2025). "We thus next sought to determine if disruptions in BECLIN-1 signaling can affect SNI-induced increases in anxiety-like behaviors by using the elevated plus maze (EPM) and open field tests (OFT) on Days 30–31 after SNI or sham procedures." (PMID 39809538, 2025). "Our findings thus reveal a sex-specific bidirectional role of BECLIN-1 in pain and anxiety-like behavior." (PMID 39809538, 2025). "The effects of BECLIN-1 disruption on nociceptive thresholds and anxiety-like behaviors suggest the possibility that BECLIN-1 activity is altered by neuropathic pain." (PMID 39809538, 2025). "In this manuscript, we use female and male mice to discover a novel role for BECLIN-1 in neuropathic pain and comorbid anxiety-like behaviors in mice." (PMID 39809538, 2025). "We found that disruptions of Beclin-1 reduce nociceptive hypersensitivity while preventing pain-induced increases in anxiety-like behaviors." (PMID 39809538, 2025). "Remarkably, whereas BECLIN-1 disruption enhanced nociceptive hypersensitivity in male mice exposed to SNI, we found that it conversely blocked SNI-induced increases in anxiety-like behaviors." (PMID 39809538, 2025). "This indicates that BECLIN-1 may prevent pain hypersensitivity and promote pain-induced increases in anxiety-like behaviors in male mice, but not in female mice." (PMID 39809538, 2025). "Notably, male mice with disruptions in BECLIN-1 that suffered from chronic neuropathic pain did not demonstrate the robust increases in anxiety-like behavior that we observed in male WT mice, suggesting that decreases in autophagy reduce anxiety-like behavior." (PMID 39809538, 2025). "We also observed that whereas disruptions of BECLIN-1 prevented pain-induced increases in anxiety-like behavior, there is an effect of BECLIN-1 disruption on exploratory behavior, suggesting that anxiety-related effects of BECLIN-1 disruption may not be limited to pain." (PMID 39809538, 2025).
Aortic dissection (1 paper, 2020). Aortic dissection refers to a tear in the intimal layer of the aorta causing a separation between the intima and the medial layers of the aorta. "Overall, these findings suggest that EHMT2 functions as a crucial negative regulator of ACD via decreasing SQSTM1 or BECN1 expression and that EHMT2 could be a potent therapeutic target for cardiovascular diseases (e.g., aortic dissection)." (PMID 32174799, 2020).
Ascites (1 paper, 2018). Accumulation of fluid in the peritoneal cavity (between the layers of the peritoneum that lines the abdomen). "IHC showed that LC-3 and Beclin-1 expression levels were increased in the re-ascites group; in contrast, CASP-9 and c-CASP-3 expression levels were reduced." (PMID 29549251, 2018). "In re-ascites cases, CA125, MDR1, LC-3, and Beclin-1 were highly expressed." (PMID 29549251, 2018).
benign cystadenomas (1 paper, 2013). "Moreover, our IHC results demonstrated that an increasing frequency of decreased expression of Beclin 1 was observed from benign (cystadenoma) to borderline tumors, and to malignant carcinomas." (PMID 23573264, 2013).
benign salivary gland tumor (1 paper, 2022). "In the present study, the results of RT‐qPCR showed PRRX1 was significantly enhanced, while LC3B and BECLIN 1 were declined in SACC tissues compared with normal tissues (NT) of the periphery of benign salivary gland tumor." (PMID 35032368, 2022).
Bethlem myopathy (1 paper, 2012). A usually autosomal dominant inherited movement disorder caused by mutations in the COL6A1, COL6A2, and COL6A3 genes. "Notably, Beclin 1 protein levels are also lowered in muscle biopsies of patients affected by collagen VI diseases, and the amount of Beclin 1 seems to correlate with the severity of the phenotype, being much lower in the severe Ullrich CMD than in the milder Bethlem myopathy." (PMID 24710479, 2012).
Calcium oxalate nephrolithiasis (1 paper, 2018). The presence of calcium- and oxalate-containing calculi (stones) in the kidneys. "Our studies observed significantly accumulated LC3 and BECN1 by immunohistochemistry staining in calcium oxalate nephrolithiasis samples." (PMID 29435125, 2018).
cerebrovascular disease (1 paper, 2021). "Previous studies demonstrated that there were autophagy disfunctions mediated by Beclin-1 in brain tissues of diabetic mice, which might accelerate the development of cerebrovascular disease." (PMID 34665375, 2021).
cholesteatoma (1 paper, 2024). A pathologic process characterized by the proliferation of keratinizing squamous epithelium resulting in the accumulation of keratin and cells in the middle ear and/or mastoid. "Additionally, beclin-1 expression levels were significantly higher in the cholesteatoma epithelium than in EAC epithelium (p = 0.001)." (PMID 38391409, 2024).
choriocarcinoma (1 paper, 2015). An aggressive malignant tumor arising from trophoblastic cells. "This indicates the Beclin-1 expression potential as a tumor marker for diagnosis and determination of prognosis towards choriocarcinoma." (PMID 26494988, 2015). "In contrast to the weak expression of Beclin-1 with low total score averages of immunoexpression in moles, there is peculiarity in choriocarcinoma in the form of strong expression of Beclin-1 with a high total score average." (PMID 26494988, 2015). "On the other hand, the strong Beclin-1 expression was dominant in choriocarcinoma with total score average of 4.57 ~ 5, so that it had a significantly diffferent Beclin-1 immuno-expression total score (p<0.05) from the three types of mole." (PMID 26494988, 2015). "The three molar types had significantly different Beclin-1 immunoexpression from choriocarcinoma (p = 0.032, p = 0.016, p = 0.038, respectively)." (PMID 26494988, 2015). "Bcl-2 and Beclin-1 immunoexpression were studied on complete hydatidiform mole, partial hydatidiform mole, invasive mole, choriocarcinoma and normal placenta slides." (PMID 26494988, 2015). "The total score average of Beclin-1 immunoexpression for choriocarcinoma was 4.57." (PMID 26494988, 2015). "The decreased expression of Beclin-1 that leads to autophagy defects in complete hydatidiform mole, partial hydatidiform mole and invasive mole shows the role of autophagy as tumor suppressor, whereas strong Beclin-1 expression shows the survival role of autophagy in choriocarcinoma." (PMID 26494988, 2015).
Chronic colitis (1 paper, 2024). A chronic inflammatory disease of the large intestine (colon, cecum and rectum). "However, upon treatment with either 5 mg/kg or 10 mg/kg of BMS-477118, the levels of ULK1 and Beclin 1 in the chronic colitis group were significantly increased compared to the untreated chronic colitis group (respectively)." (PMID 39359253, 2024). "In untreated rats with chronic colitis, there was a significant decrease in the levels of ULK1 and Beclin 1 compared with the control, healthy group." (PMID 39359253, 2024).
chronic hepatitis B (1 paper, 2025). "While our study highlights the clinical correlations between Beclin-1, the Nrf2-Keap1 pathway, and HBeAg seroconversion in chronic hepatitis B (CHB), it is critical to contextualize these findings within the intricate interplay of HBV pathogenesis, autophagy, and oxidative stress." (PMID 41035887, 2025).
clear cell carcinomas (1 paper, 2014). "We could not compare with this study, as in our series we had only 4 cases of clear cell carcinomas, 2 each either BECLIN 1 positive or BECLIN 1 negative." (PMID 25136588, 2014).
dengue virus infection (1 paper, 2020). "Other canonical autophagy factors, specifically ULK1, Beclin-1, and ATG5 are dispensable during dengue virus infection." (PMID 33173007, 2020). "Autophagy components that enhance dengue virus infection include VPS34, a kinase present in complex with Beclin-1 and needed for initiation of canonical autophagy; ATG9, which is involved in lipid acquisition; and LC3, which is needed for cargo loading and induction of membrane curvature." (PMID 33173007, 2020).
dermatomyositis (1 paper, 2025). Dermatomyositis (DM) is a type of idiopathic inflammatory myopathy characterized by evocative skin lesions and symmetrical proximal muscle weakness. "It was demonstrated that the expression of GRP78/BiP, an ER chaperone protein and autophagy-related 12 (ATG12) protein and Beclin-1, involved in autophagy pathways, was elevated in skeletal muscles of patients with dermatomyositis and immune-mediated necrotizing myopathy." (PMID 40943287, 2025).
diffuse type adenocarcinoma (1 paper, 2020). An adenocarcinoma characterized by the presence of a diffuse cellular infiltrate which is composed of poorly cohesive cells with minimal or no glandular formations. "There was a higher Becn1 mRNA expression in intestinal- than diffuse-type adenocarcinoma according to DErricodata (P<0.05)." (PMID 33425768, 2020).
echovirus infection (1 paper, 2023). "In the present study, we also observed the up-regulation of Beclin-1 during echovirus infection." (PMID 37114059, 2023).
edema (1 paper, 2024). An abnormal accumulation of fluid beneath the skin, or in one or more cavities of the body. "It was found that the symptoms of pulmonary edema were significantly alleviated in the H/R rats treated with miR-141-3p mimic, while further overexpression of SIRT1 or Beclin-1 could reverse the effects." (PMID 38261732, 2024).
fibromyalgia (1 paper, 2021). A chronic disorder of unknown etiology characterized by pain, stiffness, and tenderness in the muscles of neck, shoulders, back, hips, arms, and legs. "Moreover, autophagy was also induced in reserpine-induced fibromyalgia, as confirmed by the significant increase in the gene expression of the autophagy markers (LC-3, BECN-1) in the reserpine-treated group that was significantly ameliorated by fisetin treatment." (PMID 35011610, 2021).
Follicular Cyst (1 paper, 2024). Cyst due to the occlusion of the duct of a follicle or small gland. "In this study, compared with the estrus cows, the levels of the autophagy-related proteins LC3B2 and BECN1 were found to be significantly decreased in GCs from follicular cysts." (PMID 39232832, 2024).
fungal keratitis (1 paper, 2023). "Available data suggests that miRNAs, Beclin 1, and the cGAS-STING pathways may play key roles in mediating autophagy during fungal keratitis." (PMID 37153108, 2023).
gestational trophoblastic disease (1 paper, 2015). "The change of Bcl-2 activity as antiapoptosis and Beclin-1 as proautophagy plays a role in pathogenesis of gestational trophoblastic diseases." (PMID 26494988, 2015).
GM1 gangliosidosis (1 paper, 2023). A rare lysosomal storage disorder characterized biochemically by deficient beta-galactosidase activity and clinically by a wide range of variable neurovisceral, ophthalmological and dysmorphic features. "Although the elevated level of Beclin-1 has been shown in npc1-/- mice, fibroblasts of Niemann-Pick patients, and β-gal-/- mouse brain of GM1 gangliosidosis, the level of Beclin-1 has not changed in mice model of multiple sulphatase deficiency (MSD) and mucopolysaccharidosis type IIIA (MPS-IIIA)." (PMID 36928510, 2023).